TGM2 (transglutaminase 2)
Diseases named in the same sentence as TGM2 in open-access papers (continued):
Sharing a sentence is not in itself a finding about the gene and the disease.
renal cell carcinoma (18 papers, 2015 to 2023).
renal fibrosis (17 papers, 2011 to 2025). A final common manifestation of a wide variety of chronic kidney diseases characterized by glomerulosclerosis and tubulointerstitial fibrosis. "Our results are in line with other reports examining TGM2 function in several tissues using in vivo models of cardiac, pulmonary, and renal fibrosis, in which TGM2 inhibition or gene deletion resulted in reduced tissue remodeling and scarring." (PMID 39800950, 2025). "To determine the role of TGase2 in hyperglycemia-induced vascular leakage and renal fibrosis in the diabetic kidney, we utilized Tgm2−/− mice." (PMID 35054938, 2022). "The expression of Tgm2 is increased by exposure to advanced glycation end products and is suggested to induce renal fibrosis in the aging kidney." (PMID 28859164, 2017). "From both studies, however, it is difficult to conclude if Tgm2 is a marker of CAI reflecting changes in the cellular composition of the graft or actively contributes to the pathogenesis of CAI as shown for diverse models of experimental renal fibrosis." (PMID 26063971, 2015). "In the feline renal fibrosis process, several major pro-fibrotic mediators are involved, including TGF-β, transglutaminase 2 (TG2), endothelin 1 (ET1), and the renin-angiotensin-aldosterone system (RAAS)." (PMID 39858257, 2025). "IFN-γ can induce the production of profibrotic factors, such as transglutaminase 2 (TG2) and the heparan sulfate proteoglycan syndecan-4 (sdc4) that contribute to the accumulation of extracellular matrix, thus favoring the development of renal fibrosis." (PMID 32903887, 2020).
pulmonary fibrosis (16 papers, 2013 to 2025). Chronic progressive interstitial lung disorder characterized by the replacement of the lung tissue by connective tissue, leading to progressive dyspnea, respiratory failure, or right heart failure. "Interestingly, we also show that activation of Adora2b modulates expression of Tgm2, a multifunctional enzyme that has been associated with PH and pulmonary fibrosis." (PMID 29910735, 2018). "TGM2 has been shown to be important in studies using in vitro and in vivo models of kidney and lung fibrosis." (PMID 39800950, 2025). "We show enhanced levels of TGM2 in scleroderma fibroblasts; observations consistent with previous studies of idiopathic pulmonary fibrosis lung fibroblasts which also showed raised TGM2 levels." (PMID 39800950, 2025). "Previous studies in renal and pulmonary fibrosis have similarly observed extensive TGM2 expression and activity within a number of cells in fibrotic lesions." (PMID 39800950, 2025). "Tissue transglutaminase 2 (TG2) is believed to promote lung fibrosis by crosslinking extracellular matrix components and activating latent TGFβ." (PMID 38959068, 2024). "Concordantly, the genes encoding transglutaminases (TGM1, TGM2 and TGM5), which are enzymes responsible for crosslinking and also involved in pulmonary fibrosis, were significantly upregulated." (PMID 32698440, 2020). "In our experimental model of BLM-induced lung fibrosis and PH, we report increased levels of Has2, Il-6 and Tgm2 following BLM exposure compared to PBS exposure in TaglnCre mice." (PMID 29910735, 2018). "Exogenous TGM2 activates lung fibroblasts, which is relevant to idiopathic pulmonary fibrosis." (PMID 39800950, 2025). "Here, we show that transglutaminase 2 (TG2), previously reported to elicit a TH17 response by increasing IL-6 expression in a mouse model of lung fibrosis, mediates the upregulation of cytokines and chemokines by activating NF-κB in imiquimod (IMQ)-treated keratinocytes." (PMID 32355189, 2020).
fibrosis (15 papers, 2014 to 2025). the formation of excess fibrous connective tissue in an organ or tissue in a reparative or reactive process. "Cardiac fibrosis was apparent at 8 weeks of age in some Tgm2/F13a1 double knockout mice." (PMID 31874419, 2020). "Cardiac fibrosis developed in both Apoe/F13a1 double knockout and F13a1 single knockout mice, but not in Tgm2 knockout mice." (PMID 31874419, 2020).
Hypertension (15 papers, 2011 to 2025). The presence of chronic increased pressure in the systemic arterial system. "There were several genes affected by high-intensity interval training during HFD hypertension, which were Trim39, Nr4a1, Plekhf1, Tgm2, Lgals1, Egr1, and Atf3." (PMID 41516177, 2025). "In the context of hypertension, Tgm2 and other active transglutaminases were shown to contribute to the pathogenesis of vascular remodeling." (PMID 26063971, 2015). "TGM2 and SPHK1 have, e.g., both been associated with hypertension." (PMID 38791593, 2024). "Protein-glutamine gamma-glutamyltransferase 2 (TGM2), which co-immunoprecipitated with MDMX and PICALM, catalyzes protein cross-linking, is considered a bridge between inflammation and hypertension, and is upregulated in preeclampsia." (PMID 38594674, 2024).
colon carcinoma (14 papers, 2011 to 2023). "A previous study has shown that overexpression of TGM2 mRNA is associated with reduced OS in colon cancer." (PMID 37443286, 2023). "A recent study showed that the invasion of SW480 colon cancer cells was significantly enhanced by the inhibition of TGM2 protein expression." (PMID 37115802, 2023). "Our data are consistent with the tumor-promoting role of TGM2 observed in breast, ovarian and colon cancer cells." (PMID 37443286, 2023). "TGM2 regulates the angiogenesis of digestive system tumors through the WntB-catenin pathway and interferes with the apoptosis of colon cancer cells." (PMID 35669563, 2022). "Although other groups have studied the role of TGM2 in colon cancer, the results are controversial, partly due to the pleiotropic functions of TGM2." (PMID 34103685, 2021). "In primary patient material of CRC patients, we detected an increased expression and enzymatic activity of TGM2 in colon cancer tissue in comparison to matched normal colon mucosa cells." (PMID 34103685, 2021). "Others have similarly shown that TGM2 expression is a prognostic marker in colon cancer and non-small cell lung cancer; and in proteomic profiles, TGM2 upregulation in HCC correlates with early recurrence." (PMID 30393774, 2018).
hepatocellular carcinoma (14 papers, 2011 to 2025). A malignant tumor that arises from hepatocytes. "TGM2, a candidate marker for hepatocellular carcinoma and EpCAM (epithelial cell adhesion molecule) were highly expressed in Hep3B-EVs and HepG2-EVs, but only faintly in HuH7-EVs and HuH6-EVs." (PMID 29137313, 2017).
atherosclerosis (13 papers, 2014 to 2025). A disease characterized by the build-up of fatty material and calcium deposition in the arterial wall resulting in partial or complete occlusion of the arterial lumen. "We can, however, not exclude that extracellular transglutaminase activity is involved in both remodeling and re-remodeling of graft arteries as a protective effect of Tgm2 was reported for experimental atherosclerosis." (PMID 26063971, 2015). "Transglutaminase 2 (TG2) cross-links extracellular matrix proteins and has a complex role in atherosclerosis, participating in the initial stages of plaque formation, while its deficiency could be associated with unstable atherosclerotic plaques in mice." (PMID 37176139, 2023). "Finally, during the development of CAI, Tgm2 might protect graft blood vessels as already evidenced in the context of atherosclerosis." (PMID 26063971, 2015). "Using a Venn diagram to identify the shared genes, we identified six candidate downstream molecules potentially regulated by AP‐1 and involved in vascular endothelial dysfunction and atherosclerosis induced by OSS: NR4A1, ZNF467, LGAL59, OAS1, OAS2, and TGM2." (PMID 40492401, 2025).
Hyperglycemia (13 papers, 2017 to 2026). An increased concentration of glucose in the blood. "Here, we investigated whether p38α mitogen-activated protein kinase (MAPK) activates transglutaminase 2 (TGase2) through reactive oxygen species (ROS) generation, thereby promoting hyperglycemia-induced vascular permeability in diabetic retinas." (PMID 41750573, 2026). "In μg-conditions resulting in detached cellular structures, including spheroids and multicellular structures, hyperglycaemia increased the size and the number of spheroid structures, decreased fibronectin and transglutaminase-2, and increased NF-κB, NOX4, and caspase-3." (PMID 36830559, 2023). "Moreover, hyperglycaemia caused more pronounced changes in 3D cultures than in 2D cultures, including bigger and a greater number of spheroids, upregulation of NOX4 and the apoptotic proteins NF-κB and CASP3, and downregulation of fibronectin and transglutaminase-2." (PMID 36830559, 2023). "In contrast, hyperglycemia did not induce glomerular vascular leakage in diabetic Tgm2−/− mice compared with non-diabetic Tgm2−/− mice." (PMID 36782199, 2023). "In contrast, hyperglycemia did not induce pulmonary vascular leakage in diabetic Tgm2−/− mice compared with non-diabetic Tgm2−/− mice." (PMID 36782199, 2023). "In contrast to the high levels of FITC-dextran extravasation observed in kidneys of diabetic wild-type (C57BL/6) mice, we found that hyperglycemia did not induce vascular leakage in kidneys of diabetic Tgm2−/− mice." (PMID 35054938, 2022).
psoriasis (13 papers, 2013 to 2025). An autoimmune condition characterized by red, well-delineated plaques with silvery scales that are usually on the extensor surfaces and scalp. "We aimed to evaluate whether ablation of the TGM2 or TGM3 gene affected the severity of psoriasis markers in the context of imiquimod-treated TG3 and TG2 null mice." (PMID 32106600, 2020).
breast tumors (12 papers, 2011 to 2024). "This is in contrast to previous studies that have evaluated the prognostic significance of TGM2 in breast tumours, all of which found that increased expression was associated with a poorer prognosis." (PMID 39516660, 2024). "Other studies have shown that epigenetic silencing of TGM2 occurs in primary breast tumors, including invasive tumors and ductal carcinoma in situ (DCIS)." (PMID 37115802, 2023). "They suggest that the function of TGM2 in breast tumours depends on hormone-receptor-status and differs depending on whether it is expressed inside or outside of the cell." (PMID 39516660, 2024). "A study by Shinde and colleagues showed that overexpression of tissue transglutaminase-2 (TG2) in breast tumor cells is sufficient for augmenting the development of metastatic niches and promotion of distant metastasis, whereas TG2 depletion suppresses metastasis." (PMID 35145911, 2021). "To further test our hypothesis in cancer patient samples we stained for TGM2 in whole mount breast tumors." (PMID 33294017, 2020). "Elevated expression of TG2 may be connected with epigenetic alterations, as in doxorubicin-resistant breast tumor cells that have high levels of TG2 and hypomethylated TGM2 promoter, while doxorubicin-sensitive cells have a hypermethylated promoter." (PMID 30200219, 2018). "The decrease in TG2 expression in primary tumors may be achieved by epigenetic gene silencing, since the hypermethylation of CpG islands partly covers both the transcriptional and translational start sites of the TGM2 gene in cultured human breast tumor cells." (PMID 30200219, 2018).
chronic kidney disease (12 papers, 2012 to 2026). Impairment of the renal function secondary to chronic kidney damage persisting for three or more months. "Transglutaminase 2 (TG2) is strongly implicated in the fibrotic remodeling that drives chronic kidney disease (CKD)." (PMID 35041708, 2022). "TGM2 (transglutaminase 2) is a Ca2+-dependent enzyme involved in processes such as wound healing, apoptosis, and inflammation, and is a biomarker for chronic kidney disease." (PMID 41300790, 2025). "Transglutaminase-2 (TG2) is a new anti-fibrotic target for chronic kidney disease, for its role in altering the extracellular homeostatic balance leading to excessive build-up of matrix in kidney." (PMID 27694984, 2016).
liver disease (12 papers, 2011 to 2023). "Chronic alcohol use has been shown to provoke an IgA response that is not only directed towards alcohol metabolites but also against self antigens, targeting the enzyme transglutaminase 2 (TG2), even in the absence of liver disease." (PMID 27729985, 2016).
non-small cell lung carcinoma (12 papers, 2011 to 2025). A group of at least three distinct histological types of lung cancer, including non-small cell squamous cell carcinoma, adenocarcinoma, and large cell carcinoma. "Recently, it was also suggested that transglutaminase 2 (TGM2) is a cisplatin resistance marker in non-small cell lung cancer." (PMID 21747690, 2011). "For instance, TGM2 regulates autophagic function by interacting with LC3B, contributing to enhanced radioresistance in non-small cell lung cancer stem-like cells." (PMID 41469519, 2025). "In addition, TGM2 levels were upregulated in AML and TGM2 was identified as an independent prognostic factor in non-small cell lung cancer." (PMID 40269271, 2025).
asthma (11 papers, 2010 to 2025). "Transglutaminase 2 (TG2) has been implicated in many respiratory diseases including asthma." (PMID 34099759, 2021). "The TGM2 gene is located on chromosome 20q11.2-12 near a cluster of genes related to epithelial barrier function in close proximity to a region linked to both atopic dermatitis and asthma." (PMID 20052409, 2010). "In addition to effects on eicosanoid metabolism TGM2 also activates the transcription factor NFκB that is broadly implicated in the generation of pro-inflammatory cytokines in asthma and other inflammatory diseases, and induces iNOS via NFκB." (PMID 20052409, 2010). "Transglutaminase 2 (TG2) is crucial in the development of asthma by alternatively activating alveolar macrophage as well as augmentation of Th2 response." (PMID 33945658, 2021). "The proportion of macrophages expressing mannose receptors and transglutaminase 2 in lung biopsies of patients with asthma was also significantly increased." (PMID 34608825, 2021). "Concomitantly, polymerized forms of OPN (similar to the structure of OPN, which was polymerized by TGM2) were detected in mice with asthma and enhanced after exposure to viruses." (PMID 32009132, 2020). "Polymerization of OPN is thought to be performed by TGM2, which a recent report has suggested to be increased in asthma." (PMID 22031818, 2011). "We found that TGM2 gene expression and secreted protein are increased in the airways of subjects with asthma, and further increased in the EIB+ phenotype." (PMID 20052409, 2010). "This study found that TGM2, a mediator that is novel to asthma pathogenesis, is overexpressed in asthmatic airways and functions to increase sPLA2-X enzymatic activity." (PMID 20052409, 2010). "A gene novel to asthma pathogenesis, transglutaminase 2 (TGM2), was the most differentially expressed at baseline between the groups." (PMID 20052409, 2010). "In studying the function of TGM2 in asthma, we demonstrated that TGM2 enzymatically modifies sPLA2-X leading to a substantial increase in the PLA2 activity of the enzyme." (PMID 20052409, 2010). "In vitro studies using recombinant human enzymes reveal that TGM2 augments the enzymatic activity of secreted phospholipase A2 (PLA2) group X (sPLA2-X), an enzyme recently implicated in asthma pathogenesis." (PMID 20052409, 2010). "Instead, we found that TGM2 was highly upregulated by virus infection in older mice with asthma." (PMID 32009132, 2020). "As such, inhibition of TGM2 activity or higher proteolytic cleavage may be the more likely explanations for the presence of lower polymeric sOPN that we observed in asthma." (PMID 22031818, 2011). "Further, TGM2 causes a sustained increase in sPLA2-X activity, identifying a novel mechanism by which increased expression of TGM2 may serve to amplify airway inflammation in asthma." (PMID 20052409, 2010). "Since PLA2 serves as the first rate-limiting step leading to eicosanoid formation, these results suggest that TGM2 may be a key initiator of the airway inflammatory cascade in asthma." (PMID 20052409, 2010). "Although TGM2 has been implicated in a number of inflammatory diseases, and has been shown to be upregulated by retinoic acid in transformed airway epithelial cells, it has not been previously implicated in asthma." (PMID 20052409, 2010). "This hypothesis is further complemented by the M2 polarization profile (APOE, TXN, TGM2, STING1, NAMPT) enriched in this group, a dominant macrophage profile in high Th2-type asthma in humans and one known to activate the Th2 response with downstream eosinophilic infiltration and airway remodeling." (PMID 39594673, 2024). "We confirmed that the TGM2 protein is increased in airway cells and airway lining fluid in the EIB positive group, and that both asthma groups have increased levels relative to a non-asthmatic control group." (PMID 20052409, 2010).
asthma (continued). "Based on differences in gene expression, we confirmed that transglutaminase 2 (TGM2) was over-expressed in airway cells by quantitative PCR (qPCR), and that the TGM2 protein is elevated in the airway lining fluid of asthmatics with EIB relative to the asthma group without EIB." (PMID 20052409, 2010).